NRAS (NRAS proto-oncogene, GTPase)
Diseases named in the same sentence as NRAS in open-access papers (continued):
Sharing a sentence is not in itself a finding about the gene and the disease.
melanoma (continued). "We compared our candidate drugs to known anti-melanoma and NO-based drugs using publicly available drugs screens and high-throughput CRISPR data and experimentally validated six of these candidates in BRAF and NRAS mutated cell lines in mono and combination treatment with BRAF/MEK inhibitors." (PMID 37495601, 2023). "However, pathologic melanoma subtype and NRAS mutation were not significantly correlated with ORR, DCR." (PMID 36600247, 2023). "Recently, miRNome and proteome profiling of extracellular vesicles (EVs) isolated from BRAF- or NRAS-mutant melanoma cells cultured under hypoxia revealed distinct changes in several factors that could potentially be tested as biomarkers for melanoma progression." (PMID 36901857, 2023). "Currently, there are no approved target therapies for NRAS-mutated melanoma." (PMID 37373134, 2023). "Also, the co-occurrence of NRAS and BRAF, the two most frequently mutated genes in melanoma, is also rarely reported (2.9%), which is in agreement with our observations as we found concomitant NRAS/BRAF variants in 5 (1%) of our melanoma samples; however, their clinical impact is not known." (PMID 37483495, 2023). "To investigate whether miR-708 is a suitable drug for cancers driven by NRAS mutation, we collected three cell lines carrying NRAS mutation from different cancer types, SK-MEL-2, THP-1, and H1299, which belong to malignant melanoma, AML, and non-small cell lung cancer (NSCLC) respectively." (PMID 37083947, 2023). "Nevertheless, binimetinib proved to be advantageous in the treatment of melanoma in vivo and led to high rates of apoptosis in vitro; hence, it still seems to be a good base for combination with other substances in the treatment of patients with NRAS-mutant melanoma." (PMID 38067230, 2023). "Interestingly, the enforced expression of these miRNAs is not able to affect the proliferation of BRAF-wt melanoma cells either in the absence or in the presence of NRAS mutations, thus suggesting their specificity only for BRAF-mutated melanomas." (PMID 36418472, 2023). "The growth of a BRAF or NRAS mutant nevus is limited by cell-cycle arrest and cellular senescence, which may be interrupted by genetic and genomic disruption of tumor suppressor genes to allow the progression of the lesion to melanoma." (PMID 36834954, 2023). "Some investigations have reported mutually exclusive patterns, suggesting that TERT promoter mutations may represent an alternative pathway of telomerase activation in melanoma cases lacking BRAF or NRAS mutations." (PMID 37504268, 2023). "Overall, these findings provide a new molecular method to classify melanoma patients carrying BRAF and NRAS mutations and help provide a broader view of the molecular characteristics of these patients that may help understand the signaling pathways and interactions involving the altered genes." (PMID 36982192, 2023). "Interestingly, NRAS mutations have been described in chondrosarcomas, but the particular variant found in this melanoma has not been found in chondrosarcomas." (PMID 37373134, 2023). "Notably, the sorafenib/trametinib combination has already been applied in the context of BRAF class III mutations and advanced hepatocellular carcinoma, while first clinical data on naporafenib/trametinib combinations have recently been published for NRAS-driven melanoma." (PMID 37656784, 2023). "However, mucosal melanomas tend to differ from their cutaneous counterparts in terms of molecular profiling; albeit showing a heterogeneous molecular profile, they have lower BRAF and TERT, and relatively higher NRAS and KIT mutation frequencies." (PMID 35642348, 2023). "One or more combinations of MEK inhibitors with either anisomycin, rapamycin, chloroquine/bafilomycin, and cytochalasin modulate p38 activation, mTOR phosphorylation, autophagy, and actin polymerization, respectively, and they may provide an alternate route to targeting NRAS-mutant melanoma." (PMID 36765834, 2023).
melanoma (continued). "BRAF (B-rapidly accelerated fibrosarcoma) and NRAS (N-Rat sarcoma virus) mutations, which are found in 50 and 20% of cases, respectively, are commonly responsible for dysregulation of the MAPK (mitogen-activated protein kinase)-proliferation signaling pathway in melanomas." (PMID 36747120, 2023). "Moreover, the combination of CDK6 inhibition and a mitogen-activated protein kinase may result in cell cycle arrest and increasing in apoptosis a NRAS mutant melanoma mouse model." (PMID 36619863, 2022). "Therefore, it investigates why BRAF would be transformed higher commonly than NRAS in melanoma." (PMID 36551688, 2022). "No melanomas were observed with both NRAS and BRAFV600E mutations." (PMID 36248850, 2022). "MEK inhibitors for NF1-mutation melanoma: Although NF1-mutant melanoma patients do not usually express NRAS or BRAF mutations, inhibition of the BRAF, MEK and mTOR pathways may be therapeutic since the NF1 mutation increases RAS/MAPK pathway signalling." (PMID 36232957, 2022). "However, in clinical studies, the influence of NRAS gene mutation status (mutation or wildtype) on melanoma immunotherapy has not been decisively proven." (PMID 35967450, 2022). "Studies have shown the emergence of NRAS, MAP2K1, AKT1, and PIK3CA mutations in patients treated with targeted therapy, which are known to be mechanisms of resistance to MAPK targeting therapy in melanoma and were associated with subsequent disease progression identified on CT scan [20•, 21, 38]." (PMID 35133615, 2022). "In addition, an open label, phase Ib clinical trial is examining naporafenib (LXH254, a RAF inhibitor) in combination with either LTT462 (an ERK1/2 inhibitor), trametinib, or ribociclib (a CDK4/6 inhibitor) in NRAS or BRAFV600 mutant melanoma and non-small cell lung cancer." (PMID 35954441, 2022). "On the other hand, it is of note that rampant genetic changes in melanoma are capable of reducing apoptosis through the overexpression of B-cell lymphoma 2 (Bcl-2), loss of both Phosphatase and tensin homolog (PTEN) and nuclear factor-κB (NF-κB), and mutation of Akt3, NRAS, and BRAF." (PMID 36224606, 2022). "While trametinib looks promising for improving patient survival from BRAF mutant melanoma, a majority of patients with the NRAS mutation do not respond to MEKi-based therapy alone; only 28% of patients with NRAS-mutated melanoma achieve a stable disease with trametinib treatment." (PMID 35216449, 2022). "Notably, for melanomas with NRAS mutations, inhibition of MEK alone is not sufficient to completely inhibit the activation of downstream signaling mediated by NRAS through CDK4." (PMID 36125617, 2022). "Mutations in NRAS constitutively activate cell proliferation signaling in malignant neoplasms, such as leukemia and melanoma, and the clarification of comprehensive downstream genes of NRAS might lead to the control of cell-proliferative signals of NRAS-driven cancers." (PMID 36358254, 2022). "Tunlametinib may be a potential treatment option for NRAS-mutant melanoma." (PMID 36386136, 2022). "Combinations of targeted agents may increase efficacy in NRAS-mutant melanoma cell lines, but despite promising preclinical testing other combinations than BRAFi and MEKi have led to disappointments due to dose-limiting toxicity in phase I trials limiting their use in the clinic." (PMID 34837846, 2022). "Consequently, STK19 inhibitor ZT-12-037-01 (1a) could inhibit oncogenic NRAS-mediated melanoma growth in vitro and in vivo." (PMID 34301278, 2021). "Unfortunately, specific molecular therapy against NRAS-mutated melanoma has not been accepted yet." (PMID 34209415, 2021). "Furthermore, studies suggested that immunotherapy was more effective in patients with NRAS mutation, but some studies conclude that NRAS mutation in melanoma has a negative impact on disease outcome." (PMID 34209415, 2021). "Novel synergies were identified in NRAS‐mutant melanomas that may be therapeutically relevant." (PMID 33769711, 2021).
melanoma (continued). "However, we showed that combining MEKi with TRT induces a marked increase in apoptosis of BRAF- and NRAS-mutant melanoma cells, which could be specific to TRT irradiation or related to the spheroid 3D architecture." (PMID 33804655, 2021). "However, all this data is accurate for BRAFV600E mutated tumors, but not for melanoma with an NRAS mutation." (PMID 33921303, 2021). "In this regards, single-site biopsy of PLA1A could be considered as a diagnostic marker of BRAF-mutant metastasis in melanoma cancer, since it is sufficiently sensitive and precise in distinguishing melanoma patients with BRAF-mutated and NRAS-mutated advanced melanoma." (PMID 33723350, 2021). "Another combination of afatinib with crizotinib (a MET inhibitor) showed efficacy, was proposed as a promising alternative targeted therapy option for melanoma irrespective of BRAF/NRAS mutational status, and may overcome resistance to BRAF inhibitors." (PMID 33918490, 2021). "In general, activating NRAS mutations could be a survival advantage for sinonasal melanoma cells independent of therapy." (PMID 34072863, 2021). "Notably, it seems that NRAS-mutant melanoma could be particularly sensitive to the combined CDK4/6/BRAF/MEK inhibition." (PMID 34071228, 2021). "Moreover, the particularly low response rate of noncutaneous melanoma patients with NRAS mutation reveals the adverse impact of NRAS mutation on immunotherapy in the Asian population." (PMID 34290710, 2021). "Therefore, we hypothesized that the Rho/MRTF pathway might play a role in the intrinsic resistance of some of the NRAS mutant melanoma cells to trametinib-induced inhibition of cell viability." (PMID 33921974, 2021). "Furthermore, regarding NRAS-mutant melanoma patients, MEK inhibitors show activity." (PMID 34301278, 2021). "Nowadays, detection of NRAS mutation does not have an established predictive role, while it could add prognostic information in melanoma patient (for example, increased risk of brain metastasis)." (PMID 35008245, 2021). "Furthermore, the preclinical efficacy of the trametinib (MEK1/2i) + hydroxychloroquine combination against KRAS-driven pancreatic ductal adenocarcinoma or NRAS-driven melanoma has already led to multiple clinical trials (NCT03825289, NCT04145297, and NCT03979651) in these areas." (PMID 34298710, 2021). "However, in malignancies with frequent mutations in the MAPK/ERK pathway, such as melanomas and colon cancers, the percentage of NRAS and KRAS mutation in Asians is not higher than those in Caucasians." (PMID 34063325, 2021). "Importantly, both groups pointed out that although somatic NRAS p.Gly12Asp variant can induce CNS’s melanoma in mice, it does not seem to have any or very little potency to induce cutaneous melanomagenesis in mice." (PMID 34643354, 2021). "As melanoma is characterized by activation of MAPK signaling due to mutations in BRAF, NRAS, NF1 and KIT genes, this suggests that further hyperactivation of MAPK signaling through loss of inhibitors of this signaling pathway may be deleterious to melanoma cells." (PMID 32767816, 2021). "In addition, NRAS mutation had an association with improved OS in ipilimumab-treated melanoma compared with wild-type melanoma, although without a significant difference (12 vs. 8 months, P=0.56)." (PMID 34290710, 2021). "Similarly, we observe that NRAS mutation correlated with worse OS and MSS in mucosal melanomas." (PMID 34571863, 2021). "In addition, we compared this model to established NRAS mutant melanoma models (VM9 and VM15)." (PMID 33921303, 2021).
melanoma (continued). "We further investigated the possibility of an alternative diagnosis including either a rhabdomyosarcoma or a melanoma, both of which have recurrent NRAS mutations, but the tissue was negative for all markers specific to these tumor types (SOX10, S100, myf4, and desmin)." (PMID 32191822, 2021). "Furthermore, SBI-756 delayed the onset and decreased the incidence of NRAS-mutant melanoma in vivo." (PMID 32517051, 2020). "However, instead, for others, such as NRAS or c-KIT mutated melanoma, the mutation’s predictive power is not sufficient to identify true responders’ subpopulations." (PMID 33233603, 2020). "The evolution of melanoma, the most aggressive type of skin cancer, is triggered by driver mutations that are acquired in the coding regions of particularly BRAF (rat fibrosarcoma serine/threonine kinase, isoform B) or NRAS (neuroblastoma-type ras sarcoma virus) in melanocytes." (PMID 32878000, 2020). "The other three subtypes, as well as melanoma of unknown primary, were dominated by driver mutations in the genes of the cell cycle control (CDKN2A) and the RTK/RAS signaling pathway (BRAF, NRAS, ERRB2)." (PMID 32825510, 2020). "However, some studies showed BRAF and NRAS mutations in the same tumor samples, suggesting that these mutations are not mutually exclusive in melanoma but exhibit intra-tumoral heterogeneity." (PMID 32695793, 2020). "This implies FBXO42 may be used as a biomarker for resistance in NRAS‐mutant melanoma." (PMID 31549767, 2020). "This implies that FBXO42 may play a role in upfront resistance in NRAS‐mutant melanoma." (PMID 31549767, 2020). "Therefore, the same experiment was performed in the NRAS-mutated melanoma cell line MEL-JUSO, in which SB202190 did not block the ERK signaling." (PMID 32531927, 2020). "It appears that the mutational landscape of mucosal melanoma points out to a distinct pattern between the upper and lower regions of MM commitment with SF3B1 and KIT presenting higher mutation rates than the common drivers of cutaneous melanomas, namely BRAF and NRAS." (PMID 31949210, 2020). "The high number of NRAS mutations in cutaneous melanoma did not allow the development of effective drugs: targeting directly NRAS remains a great challenge, and the target therapy for NRAS mutant melanoma is focused on MEK inhibitors." (PMID 32850962, 2020). "Indeed, we observed an increase in the expression levels of both RAS‐GTP and pERK in FBXO42 KO samples treated and untreated with trametinib, compared to the control cells, suggesting that KO of FBXO42 in NRAS‐mutant melanoma cells leads to MAPK pathway activation." (PMID 31549767, 2020). "As oncogenic drivers, one would expect that the primary tumors are dominated by tumor cell clones carrying the activating mutation, however, there are data indicating that this is not necessarily the case; heterogeneity both for mutant BRAF and NRAS may occur in primary melanomas." (PMID 31391014, 2019). "Interestingly, the NRAS mutant M24met melanoma cell line was more sensitive to ZA than BPH." (PMID 31623406, 2019). "Moreover, the TCGA data set for skin cutaneous melanoma was analyzed to determine whether CK2α was differentially expressed between NRAS Q61 and NRAS G12 mutant melanomas." (PMID 31681616, 2019). "With the exception of one NRAS Q61R mutation, these tumors lacked point or indel mutations in known melanoma driver genes, suggesting a distinct clinical entity or an alternative path to melanoma development." (PMID 30664638, 2019). "Finally, mucosal melanomas mutated on BRAF and NRAS may also be sensitive to MEK inhibitors as well as MEK inhibitor-based combinations." (PMID 31398831, 2019). "Likewise, we have examined whether the select bacterial strains were also capable of eliciting antitumor immunity to NRAS mutant melanoma (SW1 cells), using a different mouse strain (C3H/HeN)." (PMID 30940817, 2019).
melanoma (continued). "In addition to select patients with melanomas for targeted therapy, mutational status, such as BRAF vs. NRAS mutation or p.V600E vs. p.V600K BRAF mutations may affect clinicopathological characteristics and outcomes." (PMID 31277584, 2019). "Interestingly, activation of the Akt pathway rescued the effect of magnolol in BRAF‐ and NRAS‐mutant melanoma cells suggesting magnolol might primarily be acting through the PI3K/Akt pathway." (PMID 30793515, 2019). "Now, the initiation and development of melanoma were identified to be caused by dysfunctions of oncogenic and tumor suppressor pathway, and different biomarkers have been identified to be highly significant and relevant in the context of melanoma, including BRAF, NRAS, and C-KIT." (PMID 30832692, 2019). "Interestingly, one melanoma which developed a novel NRAS non-hot-spot mutation p.(P140S) predicted by in silico approach to be benign also carried a pathogenic hot-spot KRAS mutation p.(G12C)." (PMID 31745173, 2019). "In principle, BET inhibitors (BETi) as well may override resistance to MAPK inhibitors in certain tumors (such as NRAS-mutant melanoma) by sensitizing them to apoptosis and have been shown to potently inhibit growth of solid and hematological tumor cells in vitro and in vivo in animal models." (PMID 29794999, 2018). "Consequently, ~40% of melanoma patients have tumors that are driven by aberrant NRAS signaling." (PMID 29695835, 2018). "However, stabilization of disease course noted in a metastatic melanoma patient with an NRAS activating mutation, but BRAFWT, during a phase I clinical trial suggests that the effect of 17-AAG on the NRAS mutant subset of melanomas requires further consideration." (PMID 29481571, 2018). "Recently, exome sequencing in melanoma with high heterogeneity has identified a large catalogue of recurrent somatic variants, which were found to be mostly within the B-Raf proto-oncogene, serine/threonine kinase (BRAF) and Neuroblastoma RAS viral oncogene homolog (NRAS) genes." (PMID 30544544, 2018). "To determine whether Gamitrinib could potentiate the efficacy of 6-thio-dG in melanoma cells lacking NRAS mutations, we treated NRAS-WT melanoma cells with the nucleoside analog or the mitochondrial inhibitor as single agents or in combination." (PMID 29695835, 2018). "TCF19 might participate in managing immunosuppression in NRAS‐mutant melanoma cells." (PMID 29661909, 2018). "These treatments may be effective against melanoma regardless of the mutation status of BRAF or NRAS, if the tumors are resistant to targeted treatments, or are in relapse from immunotherapy." (PMID 30185782, 2018). "A study of the RICTOR locus by CGH array in a series of 43 melanoma short-term cultures showed that RICTOR was amplified in 19 out of 43 melanoma cell lines (44%) and that amplification was independent of the BRAF and NRAS mutation status, the most frequent mutations in melanoma." (PMID 29455662, 2018). "However, BETi/MEKi combinations elicit robust anti‐tumor effects in NRAS‐mutant melanoma." (PMID 29650805, 2018).